CALML3 (calmodulin like 3)
Description:
May function as a specific light chain of unconventional myosin-10 (MYO10), also enhances MYO10 translation, possibly by acting as a chaperone for the emerging MYO10 heavy chain protein. May compete with calmodulin by binding, with different affinities, to cellular substrates.
Synonyms: CLP
Tractability: PROTAC: a small molecule that binds it is known.
Gene: Protein-coding gene on chromosome 10 (5,524,961 to 5,526,771, forward strand). Ensembl gene ENSG00000178363.
Gene Ontology:
Molecular function: protein binding; calcium ion binding
Biological process: calcineurin-mediated signaling; detection of calcium ion; regulation of release of sequestered calcium ion into cytosol by sarcoplasmic reticulum
Cellular component: extracellular exosome; centrosome; cytoplasm; myelin sheath; nucleus
Genetic constraint (gnomAD): Loss-of-function variants: 1 observed, 2.16 expected, observed/expected ratio (o/e) 0.46, 90% interval 0.16 to 1.71. That is too few expected variants to judge how well the gene tolerates losing a copy. Missense variants: 198 observed, 227.94 expected, observed/expected ratio (o/e) 0.87, 90% interval 0.77 to 0.98. Synonymous variants: 98 observed, 96.76 expected, observed/expected ratio (o/e) 1.01, 90% interval 0.86 to 1.2.
Homologues: Orthologues: chimpanzee CALML3 (100% identical), macaque CALML3 (99% identical), guinea pig CALML3 (91% identical), rat Calml3 (91% identical), mouse Calml3 (89% identical), dog CALML3 (88% identical), zebrafish calm1a (85% identical), zebrafish calm1b (85% identical), Caenorhabditis elegans cal-1 (59% identical), Caenorhabditis elegans cal-3 (52% identical), Caenorhabditis elegans tnc-2 (40% identical), Caenorhabditis elegans B0563.7 (36% identical), and 4 more. Paralogues in human: CALM1 (85% identical), CALM2 (85% identical), CALM3 (85% identical), CETN1 (49% identical), CETN2 (48% identical), CABP2 (46% identical), CALML5 (46% identical), CABP1 (44% identical), CABP4 (43% identical), CALML6 (43% identical), CABP5 (42% identical), CALML4 (40% identical), and 8 more.